CPT1A (carnitine palmitoyltransferase 1A)
Diseases named in the same sentence as CPT1A in open-access papers (continued):
Sharing a sentence is not in itself a finding about the gene and the disease.
periodontitis (1 paper, 2025). An acute or chronic inflammatory process that affects the tissues that surround and support the teeth. "Nonetheless, the epigenetic mechanism underlying CPT1A histone modification in the development of periodontitis remains elusive despite the critical role of histone PTMs in the regulation of CPT1A." (PMID 40606607, 2025). "Thus, the role of CPT1A as a potential target for bone regeneration in periodontitis-induced inflammatory bone loss remains uncertain." (PMID 40606607, 2025). "Overall, these findings demonstrate that SIRT2 binds to and deacetylates CPT1A, thereby inhibiting osteoclast differentiation and concurrently alleviating inflammation in periodontal tissues during experimental periodontitis progression." (PMID 40606607, 2025). "An experimental model of periodontitis was induced using silk ligation, and the effects of CPT1A inhibition on periodontitis were evaluated in mice treated with ETO." (PMID 40606607, 2025). "Based on these findings, we theorize that CPT1A, a key mediator in FAO, is implicated in the progression of periodontitis." (PMID 40606607, 2025). "Based on these findings, CPT1A was selected for further analysis to explore its potential role in periodontitis." (PMID 40606607, 2025). "Thus, this study aimed to investigate the role of CPT1A in experimental periodontitis through the use of both animal models and in vitro experiments to offer novel insights and potential strategies for the treatment of the condition." (PMID 40606607, 2025). "In addition, SIRT2 can downregulate CPT1A expression by deacetylating its CPT1A promoter, thereby partially delaying the progression of periodontitis." (PMID 40606607, 2025). "Thus, we hypothesize that CPT1A may play a key regulatory function in chronic inflammatory diseases such as periodontitis by regulating macrophage FAO." (PMID 40606607, 2025). "Therefore, we hypothesize that CPT1A histone acetylation may play a central role in the development of periodontitis." (PMID 40606607, 2025). "Therefore, we hypothesize that SIRT2 may play a crucial role in the onset and progression of periodontitis by deacetylating CPT1A." (PMID 40606607, 2025). "This study aims to explore the role of carnitine palmitoyltransferase 1A (CPT1A), a pivotal enzyme in fatty acid oxidation (FAO), in the pathogenesis of periodontitis." (PMID 40606607, 2025). "Since CPT1A is a crucial enzyme in FAO, the results suggest that the expression of CPT1A may be altered in periodontitis." (PMID 40606607, 2025). "Nonetheless, the role of CPT1A has not been specifically explored in periodontitis." (PMID 40606607, 2025).
Peritoneal Fibrosis (1 paper, 2023). Disorder characterized by a wide range of structural changes in PERITONEUM, resulting from fibrogenic or inflammatory processes. "Our data demonstrate for the first time that disruption of CPT1A-driven FAO in mesothelial cells might be a critical mechanism underlying PD-associated peritoneal fibrosis." (PMID 37649600, 2023). "Restoration of FAO by overexpressing CPT1A or pharmacologically activating CPT1A in mesothelial cells, impairs their transition toward profibrotic phenotype, thereby lessening the peritoneal fibrosis in the experimental PD mice." (PMID 37649600, 2023). "The functional importance of FAO in PD is further shown by improvement of the FAO in mesothelial cells, either by genetic or pharmacological restoration of CPT1A, which greatly attenuates the profibrotic effects and lessens the peritoneal fibrosis." (PMID 37649600, 2023). "The finding that PD mice injected with CPT1A inhibitor show enhanced peritoneal fibrosis, warrants future studies to determine the long-term consequences of FAO inhibitors in related patients, especially in PD patients." (PMID 37649600, 2023). "Next, we investigated whether pharmacological activation of CPT1A can protect mice from development of peritoneal fibrosis." (PMID 37649600, 2023). "Thus, enhanced TGF-β1 production during PD impairs CPT1A-driven FAO that promotes peritoneal fibrosis." (PMID 37649600, 2023). "Specifically, the CPT1A could be a therapeutic target potentially achieved by genetic overexpression or pharmacological activation, to prevent the progressive peritoneal fibrosis in PD." (PMID 37649600, 2023). "Together, our results concur in demonstrating that inhibition of CPT1A in PD fluid-treated mice dysregulates FAO and thereby contributes to peritoneal fibrosis in this mouse model of PD." (PMID 37649600, 2023). "This aberrant metabolic state could be improved by modulating CPT1A in mesothelial cells, suggesting FAO enhancement in mesothelial cells is a potential treatment of peritoneal fibrosis." (PMID 37649600, 2023). "Thus, transgenic overexpression of CPT1A in mesothelial cells, which does not impinge on glycolysis, protects mice from the development of PD fluid-induced peritoneal fibrosis." (PMID 37649600, 2023).
pneumonia (1 paper, 2022). An acute, acute and chronic, or chronic inflammation focally or diffusely affecting the lung parenchyma, caused by an infection in one or both of the lungs (by bacteria, viruses, fungi, or mycoplasma.). "Screening the Cpt1a gene for common variants predicted to affect protein function revealed allele rs2229738_T, which was associated with pneumonia risk in a targeted human phenome association study." (PMID 36513703, 2022). "The findings demonstrate that the Cpt1a rs2229738_T allele is associated with infection risk in humans and that pharmacologic inhibition of Cpt1a exacerbates infection in a murine pneumonia model." (PMID 36513703, 2022). "Cpt1a-dependent fatty acid beta-oxidation is found to regulate neutrophil trafficking to the site of infection in a mouse model of pneumonia and is found to play a role in pneumonia susceptibility in humans." (PMID 36513703, 2022). "Taken together, these data indicate that acute, systemic pharmacologic inhibition of Cpt1a-dependent FAO results in increased mortality, increased organ dysfunction, and impaired control of bacterial replication during murine pneumonia." (PMID 36513703, 2022).
Polydipsia (1 paper, 2023). Excessive thirst manifested by excessive fluid intake. "Strikingly, both male and female Cpt1aKO mice showed polydipsia and polyuria, with more reduced serum vasopressin levels in females and without osmolality alterations, indicating a direct involvement of Cpt1a in AgRP neurons in fluid balance." (PMID 36966335, 2023).
renal tubular acidosis (1 paper, 2024). A group of genetic disorders of the kidney tubules characterized by the accumulation of metabolically produced acids with elevated plasma chloride, hyperchloremic metabolic acidosis. "Consistent with this, patients with CPT1A deficiency do not have major kidney defects (some with renal tubular acidosis)." (PMID 38516886, 2024).
Right ventricular hypertrophy (1 paper, 2025). In this case the right ventricle is more muscular than normal, causing a characteristic boot-shaped (coeur-en-sabot) appearance as seen on anterior- posterior chest x-rays. "Endothelial Cpt1a deletion was further augmented, whereas nanoparticle‐mediated endothelial Cpt1a gene delivery inhibited, neonatal hyperoxia‐induced pulmonary vascular remodeling and right ventricular hypertrophy." (PMID 39799584, 2025). "Interestingly, SB431542 treatment also inhibited pulmonary vascular remodeling and right ventricular hypertrophy in EC‐specific Cpt1a knockout mice exposed to hyperoxia as neonates." (PMID 39799584, 2025).
Stroke (1 paper, 2025). Sudden impairment of blood flow to a part of the brain due to occlusion or rupture of an artery to the brain. "Crucially, human hepatocytes exhibit 10-fold higher CPT1A sensitivity than rodent models, explaining dose-limiting hepatotoxicity (ALT elevation in 60% of non-stroke trials)." (PMID 41184254, 2025). "Stroke subtype-specific interventions address distinct metabolic vulnerabilities: cardioembolic strokes with high TMAO benefit from fecal transplant and CPT1A inhibitors, while lacunar strokes with NAD+ depletion respond to NAD+ precursors and time-restricted feeding (TRF)." (PMID 41184254, 2025).
toxicity (1 paper, 2025). The degree to which an agent can damage an organism. "It is noteworthy that all target antigens (ROCK2, TOM1L1, NMD3, CPT1A, and MIT3) are expressed in normal skin according to the Human Protein Atlas, consistent with a possible relationship between autoantibodies and skin toxicity." (PMID 40828987, 2025).
triple-negative breast carcinoma (1 paper, 2025). An invasive breast carcinoma which is negative for expression of estrogen receptor (ER), progesterone receptor (PR), and human epidermal growth factor receptor 2 (HER2). "Further functional experiments suggested that Inhibition of RACGAP1 sensitizes triple-negative breast cancer cells to ferroptosis by regulating carnitine palmitoyltransferase 1 A (CPT1A)-dependent FA metabolism." (PMID 41444950, 2025).
viral infection (1 paper, 2020). "Interestingly, modulation of fatty acid metabolism has been shown to enhance CD8+ memory T cell function, however paradoxically, the fatty acid oxidation gene CPT1A has also been linked with T cell dysfunction, whereby CPT1A is upregulated in early stage exhausted T cells following viral infection." (PMID 32549336, 2020).
tumor (178 papers, 2009 to 2026). "In vivo, lactylation-deficient CPT1A mutants (K180R/K285R) attenuated lung metastasis and subcutaneous tumor growth in nude mice." (PMID 42045183, 2026). "Loss of CEBPB reduced ether lipids, reactivated CPT1A, and impaired Akt signaling, diminishing tumor growth and lipid content in vitro and in vivo." (PMID 41565622, 2026). "Functionally, the inhibition of CPT1A is essential for tumor formation, and adverse patient outcomes are associated with lower expression of CPT1A in tumors." (PMID 41421797, 2025). "FA metabolism is significantly enhanced in PTC; elevated expression of LPL, FATP2 and CPT1A was linked to tumor aggressiveness." (PMID 41041104, 2025). "Essentially, the study established a direct correlation between increased expression of the three enzymes and tumor aggressiveness: elevated levels of LPL, FATP2, and CPT1A were associated with lymph node metastasis and more advanced tumor stages." (PMID 41041104, 2025). "We further demonstrated that CPT1A inhibition rescued the reduction in tumor cell lipid content caused by MED15 loss, suggesting a novel role for MED15 in regulating hypoxia-induced lipid metabolism through the HIF-CPT1A axis." (PMID 39947475, 2025). "At the same time, the upregulation of CPT1A is associated with the enhancement of energy metabolism in tumor cells and the development of drug resistance." (PMID 41310903, 2025). "In another study using syngeneic mouse tumor models, ezetimibe treatment was shown to down-regulate mTOR2 signaling and enhance CPT1A expression, which is associated with the development of CD8+ T cell memory." (PMID 38586464, 2024). "Collectively, these data argue that loss of Cpt1a disrupts redox homeostasis in ErbB2+ tumor cells, triggering an oxidative stress response through upregulation of Nrf2 and its target genes." (PMID 39097623, 2024). "Combining the ketogenic diet, composed of LCFAs, or an anti-ErbB2 monoclonal antibody (mAb) with Cpt1a deficiency significantly perturbs tumor growth, enhances apoptosis, and reduces lung metastasis." (PMID 39097623, 2024). "As Cpt1a is modulated by multiple metabolic inputs and implicated in metabolic regulation, we examined the bioenergetic state of Cpt1a-deficient tumor cells." (PMID 39097623, 2024). "Both glucose uptake and the expression of the glucose transporter Glut1 (Slc2a1), but not that of Glut2 (Slc2a2), Glut3 (Slc2a3), or Glut4 (Slc2a4), were elevated in Cpt1a-deficient ErbB2 tumor cells." (PMID 39097623, 2024). "To further explore mechanisms involved in the altered glucose metabolism of Cpt1a-deficient cells, we first measured glucose uptake and the expression of glucose transporters in wild-type and Cpt1a-null ErbB2-driven tumor cells." (PMID 39097623, 2024). "Ablation of both Cpt1a alleles (Cpt1aL/L) significantly delayed mammary tumorigenesis and severely impaired tumor growth, correlating with reduced proliferation." (PMID 39097623, 2024). "We observed that Cpt1a-deficient tumor cells had elevated cellular ratios of NAD+/NADH and NADP+/NADPH, coupled with reduced ATP levels." (PMID 39097623, 2024). "Genetic and pharmacological loss of CPT1A function markedly suppresses the metastatic colonization of CCa cells in tumor‐draining lymph nodes." (PMID 38520724, 2024). "Elevated expression of CPT1A is associated with genetic mutations, metabolic disorders, and several cancers, including breast cancer." (PMID 39097623, 2024). "Cpt1a ablation led to elevated Nrf2 expression at the protein and mRNA levels in tumor cells in vitro and in vivo, and we validated the elevated expression of Nrf2 regulated genes in Cpt1a-deficient NIC cells compared to controls." (PMID 39097623, 2024). "Abnormal expression levels of specific molecules like LPL, FATP2, and CPT1A have been linked to tumor progression and poor prognosis." (PMID 37795451, 2023).
tumor (continued). "We also observe an association between CPT1A expression and lymph node status, tumor size, tumor burden, histological grading, human epidermal growth factor receptor 2 (HER2) status, and molecular subtype." (PMID 36735704, 2023). "Elevated FAO level mediated by CPT1A is also an essential metabolic feature of tumor-associated DCs, which ultimately leads to the secretion of immune-suppressive cytokines, such as IL-6 or IL-12, promoting Treg cell aggregation to TME." (PMID 37700339, 2023). "These associations suggest that the effect of CPT-1A overexpression is being mediated by a tendency to promote the co-option of the immune system and to dampen tumour control." (PMID 36180554, 2022). "The increased expression of CPT1A specifically in VHL- cells treated to STF-62247 is quite intriguing since high expression of CPT1A limits tumor progression in VHL-mutated tumors." (PMID 35223522, 2022). "We found that CPT1A level is significantly associated with lymph node status, tumor size, TNM stage, histological grading, human epidermal growth factor receptor 2 (HER2) status and molecular subtype in both the training and test set." (PMID 33858374, 2021). "We observed that the expression of CPT1A was associated with the tumor size (P = 0.035) and Fuhrman grade (P = 0.019) of patients using the clinical data obtained by us." (PMID 33381539, 2020). "The clinicopathological data collected by us demonstrated that the expression of CPT1A is associated with the tumor size and Fuhrman classification of KIRC patients." (PMID 33381539, 2020). "CPT1A has been implicated in tumor initiation, metastasis, and therapy resistance." (PMID 40867868, 2025). "In addition to this, elevated levels of FATP2 and CPT1A were independently linked to a dire prognosis, implying their role as prognostic markers of tumor progression." (PMID 41041104, 2025). "It is implied that CPT1A plays a pro-cancer role in most cancers, including breast, colorectal, ovarian, gastric, and lung cancers, and is closely associated with proliferation, metastasis, and drug resistance of tumor cells." (PMID 39596847, 2024). "The inability of Cpt1a-deficient tumor cells to metabolize exogenous palmitate could also be attributed to a reduction in FA uptake and the expression of Cd36, an integral plasma membrane protein that imports FAs into cells and is implicated in breast cancer." (PMID 39097623, 2024). "Consistent with the inhibitor studies, stable silencing of Nrf2 supressed proliferation, glucose consumption, and the basal and maximal OCRs in Cpt1a-deficient ErbB2+ tumor cells, but had minimal effects on wild-type cells, arguing that Nrf2 is present but not essential in these cells." (PMID 39097623, 2024). "Tumor cells derived from Cpt1a-deficient tumors proliferated at a significantly lower rate than Cpt1a-proficient cell lines in culture, arguing that the effects of Cpt1a ablation on growth are tumor cell-intrinsic." (PMID 39097623, 2024). "In pre-clinical models employing two independently derived cell lines, proficient and deficient in Cpt1a, we observed that combining 7.16.4 mAb treatment and Cpt1a deletion significantly attenuated tumor growth and proliferation and elevated tumor cell apoptosis, compared to all other conditions." (PMID 39097623, 2024). "However, Cpt1a-deficient cells exhibit increased glucose dependency that enables survival and eventual tumor progression." (PMID 39097623, 2024). "The findings suggested that CPT-1A expression and methylation is negatively associated with these cells, suggesting that survival and prognosis may be affected by inhibiting tumor-infiltrating lymphocytes (TILs) response." (PMID 37251324, 2023). "Knockdown of CPT1A can promote tumor cell susceptibility to Cisplatin." (PMID 37033619, 2023). "Serum CPT1A levels are also associated with the tumor burden of BC." (PMID 37469520, 2023).